LRRC51 (leucine rich repeat containing 51)
Tractability: Small molecule: it belongs to a druggable protein family.
Gene: Protein-coding gene on chromosome 11 (72,080,286 to 72,096,895, forward strand). Ensembl gene ENSG00000184154.
Subcellular location: Cytoplasm
Subcellular location (Human Protein Atlas): Microtubules
Pathways (Reactome):
Neuronal System: Enzymatic degradation of dopamine by COMT
Gene Ontology:
Cellular component: axoneme; cytoplasm
Genetic constraint (gnomAD): Loss-of-function variants: 9 observed, 20.02 expected, observed/expected ratio (o/e) 0.45, 90% interval 0.27 to 0.79. The upper end of that interval is the gene's LOEUF score, 0.79, which puts it in group 3 of 6, group 1 being the genes least tolerant of losing a copy. Missense variants: 233 observed, 251.48 expected, observed/expected ratio (o/e) 0.93, 90% interval 0.83 to 1.03. Synonymous variants: 92 observed, 101.69 expected, observed/expected ratio (o/e) 0.9, 90% interval 0.76 to 1.08.
Homologues: Orthologues: dog LRRC51 (90% identical), rabbit LRRC51 (90% identical), guinea pig LRRC51 (89% identical), mouse Lrrc51 (86% identical), pig LRRC51 (84% identical), rat Lrrc51 (80% identical), tropical clawed frog lrtomt (53% identical), zebrafish lrrc51 (39% identical).
Diseases named in the same sentence as LRRC51 in open-access papers:
LRRC51 is named in the same sentence as 2 diseases in open-access papers, as found by Europe PMC text mining. Sharing a sentence is not in itself a finding about the gene and the disease.
LRRC51 shares sentences with these, for which no sentence is quoted: ciliopathies (1 paper); deafness (1).